IL17A (interleukin 17A)
Diseases named in the same sentence as IL17A in open-access papers (continued):
Sharing a sentence is not in itself a finding about the gene and the disease.
infection (continued). "MMP-3 levels were significantly increased in the presence of IL-17A (above 100 ng/ml) upon infection with M intracellulare at 1000 MOI at 48 h and 72 h." (PMID 35363832, 2022). "In a mouse model of oropharyngeal candidiasis (OPC), after resting for 6 weeks following primary infection, the memory CD4+ conferred immunity to secondary infection by producing antigen-specific IL-17A responses." (PMID 36177012, 2022). "Neutrophils and IL-17A rapidly increased in the lung during early (1–2 weeks) infection, and neutrophils reappeared at 39 weeks postinfection." (PMID 35363832, 2022). "As foodborne Lm infection of adult mice induces the formation of long-lived IL-17A-producing memory Vγ4 T cells, Lm-elicited γδ T cells were assessed after foodborne infection of B6 mice with aging." (PMID 35501808, 2022). "The protective impact of IL-17A became even more clear after the infection of IL-17A−/− mice with infectious doses of Mtb H37rv higher than 1000 CFU." (PMID 36139450, 2022). "Induction of Il17a post infection was evident in ILC3s, Th17, and γδT cells, with the highest level of expression in ILC3s." (PMID 35845169, 2022). "γδT cells can rapidly produce IL-17A in the early stage of Mycobacterium tuberculosis infection, and last for 4 weeks, while CD4+T cells only produce IL-17 within the first 2 weeks of infection." (PMID 35665407, 2022). "To further assess the cellular composition of the Mtb-containing lesions in IL-17A−/− mice, we performed immunohistochemical evaluation of lung sections from C57BL/6 and IL-17A−/− mice after infection with an elevated dose of Mtb H37rv." (PMID 36139450, 2022). "Both IL-17A and IL-33 were induced after infection here, but only IL-33 is positively correlated with number of symptoms." (PMID 35479098, 2022). "We found that IL-17A-producing cells were strongly increased after infection, especially NKp46+ ILC3, the number of which was nearly double that in WT mice." (PMID 35844574, 2022). "IL-17A and GM-CSF cytokines at the site of infection protected against fungal pathogens in part by enhancing the neutrophil recruitment to the site of infection." (PMID 36177012, 2022). "As assessed by quantitative PCR, IL-17A mRNA levels are generally promoted in intestinal intraepithelial lymphocytes (IELs) after a primary infection with E. acervulina or E. maxima." (PMID 35365221, 2022). "Type 3 immunity, which is mediated by immune cells that secrete IL-17A, IL-17F, and IL-22, is likely to play an important part in the defense of the MG against infections." (PMID 35214754, 2022). "Among these data, IL-17A was significantly up-regulated within hours of infection at the transcriptional level and expression level." (PMID 35221923, 2022). "IL-17A has been shown to play a protective role in the early stages of infection by triggering macrophages and boosting Th1 effector cells." (PMID 36389696, 2022). "In contrast, these adverse effects of infection on TJs and AJs were significantly reversed by knocking-out IL-17A." (PMID 35221923, 2022). "C. sinensis infection caused diminished Th1 cytokines (IL-1β, IL-2, IL-12p70, IFN-γ and TNF-α), Th2 cytokine (IL-4), as well as Th17 cytokine (IL-17A) in sera, which showed decreasing trend by infection intensity." (PMID 36083861, 2022). "IL-17A was below the limit of detection in both Mtb-LT1 and Mtb-HT1 infected mice at week 2 post infection, however, at week 3 and 4 post infection IL-17A levels were greater in Mtb-LT1 infected mice compared to Mtb-HT1 infected mice." (PMID 35173157, 2022). "The persistence of IL-17A together with other inflammatory cytokines such as IL-12p70, stem cell factor, and IL-1β was discovered in patients up to 180 days post-infection." (PMID 36186648, 2022). "The examination of innate lymphoid cells (ILCs) in the kidney revealed a reduction in their relative cell number upon infection and only minor contribution to renal IL-17A." (PMID 35446923, 2022).
infection (continued). "At an early stage of infection, IL-17A and IL-22 from group 3 innate lymphoid cells are required for limiting C. rodentium infection and enhancing host resistance." (PMID 35844574, 2022). "We found that after 9 days of infection, there was a lower proportion of Titan cells in Il17a−/− mice compared to the fungal cells found in wild-type animals." (PMID 35208830, 2022). "The optimized approach was associated with more robust Th1 (IFN-γ, TNF-α, IL-2) and Th17 responses (IL-17A) systemically (spleens and PBMCs), but also in the lungs and draining LNs (IFN-γ and IL-17A), the primary site of infection." (PMID 36189260, 2022). "IL-17 is a mediator of inflammatory reactions in CanL, and the infection inhibited IL-17A mRNA expression in the spleen, especially in symptomatic dogs." (PMID 35324917, 2022). "In our infection model, the degree of activation of astrocytes positively correlated with the expression of IL-17A, and astrocytes were activated earlier than microglia." (PMID 35296090, 2022). "For example, the production of IL-17A can eliminate the primary infection and establish an effective memory response, and IL-17A can augment autophagy in MTB-infected monocytes from individuals with strong immunity against the bacterium." (PMID 36483566, 2022). "IL-17A is produced by Th17 cells and plays a critical role in mediating inflammation during early infection and prior to the onset of adaptive T cell responses against infectious pathogens in a variety of in vivo mammalian infection model systems." (PMID 36479344, 2022). "Among various cytokines and chemokines, IL-17A rapidly increased during the first week of infection." (PMID 35363832, 2022). "Th1 cytokines (IL-1β, IL-2, IL-12p70, IFN-γ and TNF-α), Th2 cytokine (IL-4), as well as Th17 cytokine (IL-17A) showed decreasing trend by infection intensity." (PMID 36083861, 2022). "IL-17A level increased significantly at 30 and 60 dpi compared with control following infection (P < 0.05, P < 0.05)." (PMID 35639780, 2022). "Neutralization of IL-17A during early (0–2 weeks) infection significantly reduced mortality, bacterial burden, fibrotic lung damage, and lung matrix metalloproteinase (MMP)-3 at 39 weeks postinfection." (PMID 35363832, 2022). "In primary infection due to missing T-cell response, ultimately, eradication of Shigella failed; however, in the case of secondary infection, Th17 produces IL-17A which yields restricted bacterial infection." (PMID 35718793, 2022). "In M. intracellulare-infected mice, IL-17A levels were significantly elevated during the first 2 weeks of infection." (PMID 35363832, 2022). "For example, the rs2275913 SNV, located in the promoter area of the IL-17A gene, is associated with inflammation and infection; the presence of an A allele at the rs2275913 SNV increases the secretion of IL-17A." (PMID 36591530, 2022). "For further assessment of the involvement of Th1/Th17 responses in protecting against Mav infection, we conducted in vitro experiment to evaluate the role of IL-17A and IFN-γ in terms of controlling intracellular Mav growth." (PMID 35499090, 2022). "For example, gene expression levels for IL-17A are time-point dependent, and IL-17 has been described as both a marker of infection (in M. bovis challenge experiments) as well as a correlate of BCG-induced protective immunity in cattle BCG vaccination studies." (PMID 35889984, 2022). "According to our expectations, high-dose infection with Mtb led to significantly higher bacterial burdens in IL-17A−/− mice when compared with wildtype animals by Day 29 post-infection." (PMID 36139450, 2022). "In conclusion, the higher level of effective T-cell response with IFN-γ, IL-17A, and IL-21 contributes to resolved infection outcome, while higher levels of suppressive T-cell response with IL-10 result in HBV chronicity." (PMID 35464946, 2022).
infection (continued). "Mice with previous Spn infection had faster bacterial clearance upon secondary infection in part to prolonged stability of the chemokine ligand CXCL5 transcripts by IL-17a resulting in more rapid neutrophil recruitment to the lung." (PMID 35646729, 2022). "Here, using L. major infected mice, we discovered that microbiota-dependent IL-17A–secreting ILCs promote increased disease early after infection." (PMID 34699567, 2021). "At day 30, some of the WT mice were again less often infected, however, IL-17A KO animals had also begun to clear the infection at this time." (PMID 34240122, 2021). "Induction of STM-specific IL-17A single-producing, IFN-γ/IL-17A co-producing, TNF-α/IL-17A co-producing and IFN-γ/TNF-α/IL-17A triple-producing CD4+ T cells mainly took place after infection with highest levels reached in INF animals." (PMID 34451970, 2021). "Recent studies have shown that after many pathogenic infections, CD4+ T cells can be induced to differentiate into Th17 cells, and the IL-17A expression level increases." (PMID 33879639, 2021). "The sera from STAT1−/− infected mice, obtained 8 weeks post-infection, displayed significantly higher amounts of IL-17A compared to STAT1+/+ mice." (PMID 34684235, 2021). "At 24 h before, or 6 h after infection, mice were injected with IL-17A-neutralizing antibodies through their tail veins." (PMID 33879639, 2021). "IL-17A secretion increased at the early stage of infection, and decreased after 10 days, and was then maintained at a low level." (PMID 35126348, 2021). "The result showed that the preventive treatment of IL-17A can effectively reduce the bacterial load after S. agalactiae infection, and the treatment at 6 h after infection can also play an effective role." (PMID 33879639, 2021). "In contrast, there was substantial recruitment of Siglec-F+ neutrophils to the nasal tissue of WT mice during the course of infection with B. pertussis, and this was reduced to background levels in Il17A−/− mice." (PMID 33976385, 2021). "Flow cytometric analysis after polyclonal stimulation with anti-CD3/CD28 showed that the H1-DDA/TDB-induced accumulation of IL-17A-producing cells within the CD44+CD4+CD90+ population at week 2 post-infection was highly impaired in IL-23p19−/− mice." (PMID 34351501, 2021). "Firstly, they observed that infected individuals had higher serum levels of IL-17A than healthy controls and that infection of human PBMCs with WNV led to the increased expression of IL-17A mRNA and cytokine secretion." (PMID 34064728, 2021). "For example, a recent study has elucidated the role of IL-17A in the promotion of Th2 immune responses in the lung following infection with T. muris utilizing global IL-17a knockout mice." (PMID 33952360, 2021). "During infection with S. tm., in line with the observations from the eSPF mice, we detected increased frequencies and absolute numbers of IL-17A-IL-22+ and IL-17A+IL-22+ CD4+ T cells in cecal LPLs from S. tm. infected SFB colonized GF mice." (PMID 34566952, 2021). "During the immune response to infection, IL-22 and IL-17A are often produced concurrently and at high levels in inflamed tissues." (PMID 34805416, 2021). "Neonatal mice for example, infected with G. muris, display a prolonged course of infection and a delayed IL-17A response compared to older mice." (PMID 34011991, 2021). "As expected and consistent with the proviral role of IL-17RA signaling, MHV68 infection triggered an increase in MHV68-specific CD4 T cell population expressing IL-17A following ex vivo restimulation with immunodominant MHV68 epitopes." (PMID 33824206, 2021). "We also detected IL-17A in response to infection although the cellular source of this cytokine and its role in protection are not clear." (PMID 34179160, 2021).
infection (continued). "Remarkably, our results show that IL-33 treatment during CR infection reduced the frequencies of IL-17A-expressing CD4+ T cells within the infected colon, and the impaired IL-17A response correlated with the uncontrolled pathogen clearance." (PMID 33654214, 2021). "IL-17A, the main effector cytokine of Th17 cells, plays a differential role during primary infection with Mtb." (PMID 34351501, 2021). "The upregulation of inflammatory cytokines such as IL-2, IL-6, IL-8, and IL-17A correlated with higher severity of infection and more extreme symptoms such as organ injury." (PMID 34960687, 2021). "IL-17A was found to be upregulated in all S. epidermidis infected mice, with higher systemic IL-17A cell responses in mice that cleared the infection, which was found to be produced by CD4+ and γδ+ T cells in the bone marrow." (PMID 34240122, 2021). "Inflammation is a physiological response to infection, wherein cytokines such as Interleukin-17A (IL-17A) are produced at the mucosal site to clear the host of extracellular pathogens." (PMID 33919327, 2021). "Depletion of ILCs from Rag2−/− mice resulted in reduced bacterial clearance, and anti-IL-17A treatment or infection of IL-17A−/− mice led to higher bacterial burden and mortality." (PMID 33718260, 2021). "The course of a primary infection was significantly exacerbated in Il17A−/− compared with WT mice and this was most dramatic in the nasal mucosa." (PMID 33976385, 2021). "Although Siglec-F- neutrophils also infiltrated the lungs and nasal tissue, only the infiltration of Siglec-F+ neutrophils was significantly reduced in Il17A−/− mice following primary infection or re-infection with B. pertussis." (PMID 33976385, 2021). "Serum levels of IL-17a at day 2 post-infection and IL-6, and IL-10 at day 3 post-infection are increased in TLR3+/- compared to CB4-infected wt mice." (PMID 34804036, 2021). "Further, IL-17A treatment directly supported gammaherpesvirus reactivation and de novo lytic infection." (PMID 33824206, 2021). "In the rN-BmRON2 and rC-BmRON2 groups, IL-2, IL-4, IL-6 and IL-17a levels peaked on the 21st day after infection, but then decreased rapidly." (PMID 33717108, 2021). "IL-33 and IL-17A have been separately described to play dichotomous functions in the gut depending on the infection context." (PMID 33654214, 2021). "Taken together, these and our data indicate that IL-33 and IL-17A adversely regulate the host response during infection with different intestinal bacteria." (PMID 33654214, 2021). "Accordingly, we analyzed the expression of the chemokines CXCL9, CXCL10, and CXCL11 in unvaccinated and vaccinated mice of the strains C57BL/6, IL-23p19−/−, and IL-17A−/− after infection with Mtb via quantitative real-time RT-PCR analysis." (PMID 34351501, 2021). "Our results demonstrate that basophils are the main source of IL-4 in skin superficially infected with S. aureus and that basophil-derived IL-4 dampens the protective IL-17A response against infection." (PMID 34747366, 2021). "An over-production of IL-17A at an infection site can, however, result in inflammatory tissue damage." (PMID 34209407, 2021). "Our results demonstrate that basophils are recruited following exposure of S. aureus on tape-stripped skin and that basophil-derived IL-4 acts at multiple checkpoints to inhibit the IL-17A response of TCRγδ+ T cells that protects against infection." (PMID 34747366, 2021). "We found that following infection, Il17a−/− mice, compared with wild-type mice, had significantly decreased frequencies of lung HA+ B-1a cells and HA+CD138+ B-1a." (PMID 33772013, 2021). "This provoked reduced IL-17A-producing cells (ILC3s and γδ T cells) infiltrating into the skin of Myd88−/− mice following epicutaneous infection." (PMID 34659248, 2021). "Consistently, we also found a significant increase in the number of RORγt+ IL-17A+ ILCs in L. major infected compare to control mice one-week post infection." (PMID 34699567, 2021).
infection (continued). "Nevertheless, the role of CD4 T cells, particularly Th17 cells, in the antifungal immunity to T. marneffei still needs to be further investigated by using IL-17A knockout mice infection models." (PMID 34912336, 2021). "Both G. muris and G. duodenalis infection studies in mice showed a significant upregulation of IL-17A starting one week after infection." (PMID 34011991, 2021). "IL-17A knock-out (KO) mice displayed a trend of delayed clearance of infection (P=0.22, Fisher’s exact test) and an increase in interferon (IFN)-γ production." (PMID 34240122, 2021). "At 24 h post-infection, serum levels of IL-6, IL-17A, TNF-α, and IFN-γ were greatly reduced in IL-38-treated group, CCL2 and CXCL10 decreased at day 4, IL-1β and CCL-5 decreased on day 7 in the IL-38-treated group compared with group without IL-38 treatment." (PMID 33414457, 2021). "IL-17A production correlated with the expression of Th17 transcription factor ROR gamma t upon the first infection as well as upon the second challenge, while overall frequencies were around 20% higher compared with IL17A+ CD4+ T." (PMID 33595670, 2021). "In summary, our findings reveal the need of a tightly regulated balance between IL-17A and IL-33-mediated signals for the clearance of specific enteric bacterial pathogens and the control of infection-driven intestinal immunopathology." (PMID 33654214, 2021). "Our studies on convalescent Il17A−/− mice or on WT mice treated with anti-IL-17 prior to and after re-challenge with B. pertussis demonstrated that IL-17 played a key role in adaptive natural immunity against infection in the nasal mucosae." (PMID 33976385, 2021). "The role of type I interferons, such as IFNβ, remains to be fully elucidated, as they have been implicated in both inhibiting gamma delta T cell production of IL-17A and activating the inflammasome during infection." (PMID 33946283, 2021). "IL-17A attracts neutrophils to infection sites, which is followed by promoting macrophage function; therefore, it stimulates fungicidal activity." (PMID 34209407, 2021). "To address the role of IL-17A specifically at the site of infection, we generated a genetically modified CR strain expressing and secreting IL-17A." (PMID 33654214, 2021). "The frequency of IL-17A-producing cells within the γδ T cell population was also significantly higher in the lung than those of counterparts in other organs examined, suggesting γδ T cells are the major source of IL-17A in the lung at early stage of infection." (PMID 33772013, 2021). "The blockade of IL-17A decreased, whereas rm–IL-17A exacerbated the infection-induced airway inflammation and lung dysfunction in COPD mouse models." (PMID 35095906, 2021). "Infections can generally be cleared by mounting an adequate protective immune response that is orchestrated through IL-17A." (PMID 34011991, 2021). "In contrast, another study reported that IL-17A-/- mice infected with L. donovani showed an increase in IFN-γ production by CD4+ T cells and better resistance against infection, suggesting that IL-17 promotes susceptibility to L. donovani infection." (PMID 33816344, 2021). "Together, these data suggest that IL-17A produced by γδ T cells is required to protect against pdmH1N1 infection in mice." (PMID 33772013, 2021). "The bacterial loads in the liver, spleen, lung and kidneys of mice injected with exogenous IL-17A before or after infection were significantly lower than the PBS control group." (PMID 33879639, 2021). "As IL-17A seemed to be selectively induced by the presence of S. epidermidis and IL-17A+ T cells were increased in lymph nodes of mice that cleared infection, IL-17A knock-out (KO) mice were used to study the role of IL-17A in infection clearance." (PMID 34240122, 2021).